MDM2 (MDM2 proto-oncogene)
Diseases named in the same sentence as MDM2 in open-access papers (continued):
Sharing a sentence is not in itself a finding about the gene and the disease.
breast carcinoma (continued). "MDMX (MDM4) is emerging as an important breast cancer (BC) biomarker, and oncoprotein, that can be targeted in combination with its well-known family member MDM2." (PMID 31489110, 2019). "Specifically, ERα can up-regulate the expression of MDM4 and MDM2 in some breast cancers and these effects can be blocked by endocrine therapy fulvestrant and tamoxifen." (PMID 30689920, 2019). "In vitro experiments showed that breast cancer cells transfected with amplified MDM2 were more likely to obtain drug resistance to doxorubicin." (PMID 31440117, 2019). "For example, MDM4 and EGFR were enriched in glioblastoma, MYC and ERBB2 were enriched in breast cancer whereas MDM2 was enriched in both." (PMID 30674876, 2019). "Meanwhile, XWL-1-48 evidently blocked PI3K/Akt/Mdm2 pathway, enhanced degradation of Mdm2, and suppressed breast cancer cell survival." (PMID 30176902, 2018). "The highest prevalence of MDM2 amplification was in sarcoma (57%), breast cancer (13%) and bladder cancer (9%)." (PMID 30237864, 2018). "Of the 124 patients without MDM2 amplification, 53 (43%) patients had breast cancer while of the 23 patients with MDM2 amplification, 3 (13%) had breast cancer; the Fisher exact test p-value for breast cancer was 0.0090." (PMID 30237864, 2018). "By suppressing the secretion of SASP factors such as IL-6, the MDM2 inhibitors suppressed the ability of senescent human fibroblasts to stimulate breast cancer cell aggressiveness (invasiveness and an EMT)." (PMID 29402901, 2018). "Hotspots were also identified at GNAS, RUNX1, and MDM2, all recognised as breast cancer genes, even if less frequent." (PMID 30252041, 2018). "The mechanism by which Erk activation promotes breast cancer progression via inhibition of FOXO3 expression has also been shown to be through MDM2-mediated degradation." (PMID 29915392, 2018). "Palbociclib can be used to successfully treat non-MDM2 amplified tumors, the most notable being HR+ Her2− breast cancers." (PMID 29789718, 2018). "We observed that the addition of MDM2 to breast cancer cell extracts in vitro modestly increased the phosphorylation of Rb." (PMID 28615518, 2017).
breast carcinoma (continued). "MDM2 has been shown to promote tamoxifen resistance and therefore combination-fulvestrant treatments have been proposed for patients with advanced breast cancer as a way to target the MDM2 axis." (PMID 28615518, 2017). "MDM2 has also been reported to play tumor promoting role in human breast cancer, lung cancer, and colon cancer." (PMID 28744466, 2017). "Among the genes commonly amplified or deleted in human breast cancer, only amplifications in Myc and Mdm2 and deletions of Cdkna, Cdkn4b, Csmd1 and Ptprd were seen in the mouse tumor panel." (PMID 28430642, 2017). "Combination of fulvestrant with doxorubicin, etoposide or paclitaxel is synergistic for inhibiting breast cancer proliferation and induces cell death by suppressing MDM2 expression." (PMID 28615518, 2017). "These ER+ breast cancer cell lines carry the mdm2 SNP309 T to G change and estrogen treatment induces their anchorage-independent cell growth in soft agar." (PMID 28615518, 2017). "The Cancer Genome Atlas (TCGA) data indicate that high MDM2 expression correlates with all subtypes of breast cancer." (PMID 28615518, 2017). "This argues for a true relationship between increased MDM2 in breast cancers and the activation of the Rb-E2F1 pathway." (PMID 28615518, 2017). "Melatonin drastically downregulated Mdm2 gene expression and inhibited MDM2 shuttling into the nucleus of MCF7 breast cancer cells." (PMID 28507478, 2017). "MDM2 is a multifunctional oncoprotein that is overexpressed in a variety of human malignancies, including breast cancer." (PMID 28274247, 2017). "Massive amounts of publicly available breast cancer data are available to evaluate the in vivo breast cancer relationships between MDM2 and phosphorylated Rb." (PMID 28615518, 2017). "This shows that in some ER+ breast cancer cells the knockdown of MDM2 can revert the tumorigenic 3D filled lumen phenotype to a hollow lumen phenotype." (PMID 28615518, 2017). "Researches have shown that ZEB2, TGFB1, MDM2 are important downstream effectors that can be inhibited by GATA3 in breast cancer." (PMID 28599307, 2017). "Such resistant breast cancers pose a challenge and it will be interesting to see if fulvestrant resistant breast cancers have up-regulation of MDM2." (PMID 28615518, 2017). "Our data support that an estrogen-MDM2 axis activates the Rb-E2F1 pathway in at least a subset of breast cancers." (PMID 28615518, 2017).
breast carcinoma (continued). "Studies by Huun and colleagues on MDM2 isoforms in breast cancer cells reported that approximately 85% of MDM2-FL were located exclusively in the nucleus, whereas, MDM2-A, -B, and -C were located in both the cytoplasm and nucleus." (PMID 29065514, 2017). "Many ER+ breast cancers have MDM2 overexpression suggesting that MDM2 is an ER+ axis driver oncogene that can be targeted for cancer therapy." (PMID 28615518, 2017). "Previous studies have suggested that E-cadherin is a target for MDM2-mediated ubiquitination and degradation in breast cancer cells; additionally, overexpression of MDM2 can inhibit cell—cell contact and increase cell motility." (PMID 28678832, 2017). "We have demonstrated for the first time that there is an estrogen-MDM2-Rb-E2F1 axis in some breast cancer cells." (PMID 28615518, 2017). "We examined estrogen-driven breast cancer cell growth in 3D culture and asked if MDM2 was necessary for the hormone-dependent growth properties." (PMID 28615518, 2017). "Our findings demonstrated a central function for MDM2 in the regulatory mechanism of EMT in breast cancer and expanded the repertoire of pathways that participate in this cellular process." (PMID 27184007, 2016). "In summary, triptolide has anticancer and chemosensitization effects by down-regulating Akt activation through the MDM2/REST pathway in human breast cancer." (PMID 27004407, 2016). "In this study, we investigated the role of MDM2 in epithelial-to-mesenchymal transition (EMT) and the underlying mechanisms in breast cancer cells in vitro and in vivo." (PMID 27184007, 2016). "In the present work, we report that ERα expression correlates not only with MDM2 gene expression in primary breast carcinoma samples but also with MDM4 expression." (PMID 26909605, 2016). "This is the first report to demonstrate that ERα and MDM4 exist in a protein complex with one another, and it is also the first report to demonstrate that endogenous ERα and MDM2 similarly complex with one another in breast cancer cells." (PMID 26909605, 2016). "It is well-established that MDM2 protein is coexpressed with ERα in human breast cancer cell lines and primary human breast tumors." (PMID 26909605, 2016).
breast carcinoma (continued). "Since MDM4 and MDM2 play well-characterized proliferative and prosurvival roles in breast cancer models, ERα-dependent upregulation of MDM4 and MDM2 surely enhances these processes." (PMID 26909605, 2016). "Next, we examined the effect of triptolide on MDM2 expression at protein level in these two human breast cancer cell lines." (PMID 27004407, 2016). "Since MDM2 gene amplifications are relatively infrequent, the overexpression of MDM2 in breast cancer is likely mediated by aberrant gene regulation." (PMID 26909605, 2016). "Different mechanisms proposed in embryonic fibroblasts and breast carcinoma cells included transcriptional activation of MDM2 induced by NF-kappaB transcriptional targets." (PMID 27556362, 2016). "In summary, the results from the present study demonstrated that triptolide had anticancer and chemosensitization effects in human breast cancer by targeting MDM2/Akt." (PMID 27004407, 2016). "Consistent with its oncogenic role, the MDM2 gene is overexpressed at the mRNA and protein levels in 26-73% of primary human breast cancers." (PMID 26909605, 2016). "Previous studies have demonstrated that MDM2 is overexpressed in human breast cancer and that ERα is coexpressed with MDM2 and regulates MDM2 gene expression." (PMID 26909605, 2016). "Here, we identified a small molecule (named Inulanolide A) that dually inhibited both NFAT1 and MDM2 in breast cancer cells in vitro and in vivo." (PMID 27105525, 2016). "The transcription factor NFAT1 and the oncogene MDM2 have crucial roles in breast cancer development, progression, and metastasis." (PMID 27105525, 2016). "Transgenic mice expressing HCCR developed metastatic breast cancer, and the levels of p21WAF1, MDM2, and bax decreased in the spontaneous breast cancer cells and metastatic tumours of HCCR transgenic mice." (PMID 27052330, 2016). "There are several reasons for selecting human breast cancer as the target disease for this new class of MDM2 inhibitor." (PMID 25739118, 2015). "The JapA-induced down-regulation of the MDM2 protein was confirmed by immunofluorescence detection in breast cancer cell lines." (PMID 25739118, 2015). "Second, the inhibitory effects of JapA on NFAT1-mediated MDM2 activation were demonstrated using breast cancer cells with NFAT1 OE or KD, as well as other pharmacological inhibitors and activators of calcineurin-NFAT signaling." (PMID 26461225, 2015). "Since the initial evidence for JapA-induced MDM2 inhibition was obtained with in vitro and in vivo breast cancer models, we utilized the same models in the present study." (PMID 26461225, 2015). "In colon cancer, MDM2 amplification or higher transcript abundance is associated with lower metastasis occurrence rates, while in prostate and breast cancer, elevated MDM2 expression correlates with poor outcome." (PMID 26416355, 2015). "JapA was selected as a lead compound based on its IC50 values and significant inhibitory effects on MDM2 expression in breast cancer cells." (PMID 25739118, 2015). "Stratifying according to MDM2 SNP309 status, we observed a reduced risk for breast cancer related to MDM4 SNP34091CC among individuals harboring the MDM2 SNP309GG genotype (OR = 0.41; 95% CI = 0.21–0.82)." (PMID 26471763, 2015).
breast carcinoma (continued). "In contrast, the transfection of a dominant-negative NFAT (DN-NFAT) or NFAT1 siRNA led to the downregulation of MDM2 expression, which was further enhanced by JapA in both breast cancer cell lines." (PMID 26461225, 2015). "On the contrary, up-regulation of the Mdm2 gene correlated with poor survival outcomes of patients with breast cancers." (PMID 26317544, 2015). "In the present study, we identified a new MDM2 inhibitor JapA and investigated its in vitro and in vivo anti-breast cancer activities and molecular mechanism of action." (PMID 25739118, 2015). "Taken together, these results indicated that MDM2 plays a critical role for JapA-induced anti-breast cancer activity." (PMID 25739118, 2015). "Our results would help demonstrate the therapeutic potentials of targeting MDM2 itself and provide a basis for further preclinical and clinical development of JapA as an anti-breast cancer agent, especially for the TNBC treatment." (PMID 25739118, 2015). "The MDM2 oncogene has been suggested as a molecular target for treating human cancers, including breast cancer." (PMID 25739118, 2015). "First, JapA showed stronger inhibitory effects on breast cancer cell growth and better specificity in targeting MDM2, in comparison with other candidate compounds." (PMID 25739118, 2015). "Mdmx amplification with low-level increase of gene copy number is at high frequency while Mdm2 amplification is rare in primary breast cancer." (PMID 24667108, 2014). "We also explored the Kaplan Meier Plot resource and noted that MDM2 and SFRP1 are positively associated with relapse free survival in all breast cancer subtypes, while TTK is negatively correlated with overall survival of Luminal A patients." (PMID 25278993, 2014). "We observed two two-way SNP-SNP interactions (APEX1-rs1130409 and RPAP1-rs2297381; MLH1-rs1799977 and MDM2-rs769412) in logistic regression that conferred elevated risks for breast cancer (Pinteraction<7.3×10−3)." (PMID 23755158, 2014).